SELENOF (selenoprotein F)
Description:
May be involved in redox reactions associated with the formation of disulfide bonds (By similarity). May contribute to the quality control of protein folding in the endoplasmic reticulum. May regulate protein folding by enhancing the catalytic activity of UGGT1/UGCGL1 and UGGT2/UGCGL2.
Synonyms: SEP15
Tractability: Antibody: UniProt predicts a signal peptide or a membrane-spanning region. PROTAC: ubiquitination databases record sites on it.
Gene: Protein-coding gene on chromosome 1 (86,862,445 to 86,914,424, reverse strand). Ensembl gene ENSG00000183291.
Subcellular location: Endoplasmic reticulum lumen
Gene Ontology:
Molecular function: protein binding; oxidoreductase activity; selenium binding; thioredoxin peroxidase activity
Biological process: 'de novo' post-translational protein folding; cellular oxidant detoxification; sperm DNA condensation
Cellular component: endoplasmic reticulum lumen
Genetic constraint (gnomAD): Loss-of-function variants: 10 observed, 13.11 expected, observed/expected ratio (o/e) 0.76, 90% interval 0.47 to 1.29. The upper end of that interval is the gene's LOEUF score, 1.29, which puts it in group 5 of 6, group 1 being the genes least tolerant of losing a copy. Missense variants: 167 observed, 158.89 expected, observed/expected ratio (o/e) 1.05, 90% interval 0.93 to 1.2. Synonymous variants: 65 observed, 62.79 expected, observed/expected ratio (o/e) 1.04, 90% interval 0.85 to 1.27.
Homologues: Orthologues: chimpanzee SELENOF (99% identical), macaque SELENOF (97% identical), rabbit SELENOF (94% identical), rat Selenof (92% identical), mouse Selenof (91% identical), pig SELENOF (91% identical), guinea pig SELENOF (90% identical), zebrafish selenof (78% identical), Drosophila melanogaster CG7484 (45% identical), Caenorhabditis elegans Y76B12C.3 (37% identical), tropical clawed frog selenof (33% identical). Paralogues in human: SELENOM (12% identical).
Diseases named in the same sentence as SELENOF in open-access papers:
SELENOF is named in the same sentence as 29 diseases in open-access papers, as found by Europe PMC text mining. Sharing a sentence is not in itself a finding about the gene and the disease. The quoted sentences say what the papers report.
colon carcinoma (12 papers, 2011 to 2023). "Our previous in vitro and in vivo studies using colon cancer cells with a targeted down-regulation of SelenoF or using a systemic Selenof-KO mouse model, saw a reversal of the colon cancer phenotype and a decreased number of chemically induced pre-neoplastic lesions, respectively." (PMID 34638991, 2021).
breast carcinoma (7 papers, 2013 to 2026). "In conclusion, these findings are consistent with the notion that SELENOF is a breast tumor suppressor, and its loss contributes to breast cancer etiology." (PMID 37509331, 2023). "A potential role for SELENOF in carcinogenesis in multiple organ types is indicated by several lines of evidence, including loss of heterozygosity in breast cancers and the association of specific polymorphisms of SELENOF and the risk of colorectal cancer." (PMID 34769469, 2021). "Among these, SELENOF (formerly SEP15) has emerged as a candidate implicated in breast cancer, based on initial findings of loss of heterozygosity at the SELENOF locus in breast tumor samples." (PMID 41563517, 2026). "Recent data supports a tumor suppressor function of SELENOF in breast cancer." (PMID 37509331, 2023). "Furthermore, SELENOF overexpression attenuates a number of aggressive cancer phenotypes in breast cancer cells, including clonogenic survival and mammosphere formation, and enhances the response to drugs or radiation used in breast cancer therapy." (PMID 36979420, 2023). "SELENOF, formerly known as SEP15, is one of the selenoproteins that is highly sensitive to bioavailable selenium, which itself correlates with survival of breast cancer patients." (PMID 37509331, 2023). "In this study, we explore the expression levels of SELENOF and eIF4a3, along with genotypes of SELENOF and the selenium transporter SELENOP, in breast cancer tissues from African American and Caucasian women using a tissue microarray (TMA) with relevant clinical data." (PMID 41563517, 2026).
colorectal cancer (6 papers, 2011 to 2023). A primary or metastatic malignant neoplasm that affects the colon or rectum. "SELENOH downregulated colorectal cancer cells showed increased growth properties, and loss of GPX2 and SELENOF impaired growth of colorectal cancer cells." (PMID 35433131, 2022).
prostate carcinoma (6 papers, 2012 to 2025). A carcinoma that arises from epithelial cells of the prostate gland. "One selenoprotein implicated in prostate cancer etiology is SELENOF which was originally identified as a human T cell 15 kDa protein that labels with 75Se and is expressed at high levels in the prostate." (PMID 34769469, 2021). "In conclusion, the data provided here indicates that SELENOF is a prostate cancer tumor suppressor able to alter the transformed phenotype of human prostate epithelial cells and may contribute to the disparity in prostate cancer mortality that exists among men of African descent." (PMID 34769469, 2021). "For example, GPX1, SELENOF, and SELENOP levels were significantly reduced in prostate cancer models, whereas GPX2 was significantly increased." (PMID 32933107, 2020).
selenium deficiency (3 papers, 2012 to 2025). A nutritional deficiency disease resulting from inadequate selenium levels in the body, which can lead to impaired function of selenoproteins essential for antioxidant defense and thyroid hormone metabolism. "Interestingly, several genes encoding selenoproteins (GPX1, GPX4, SELENON, SELENOM, SELENOF, SELENOW, SELENOT) were also downregulated, suggesting molecular evidence of selenium deficiency." (PMID 40459789, 2025).
AIDS (1 paper, 2022). A syndrome resulting from the acquired deficiency of cellular immunity caused by the human immunodeficiency virus (HIV). "An increasing number of studies have linked SELENOF gene polymorphisms and SELENOF dysregulation to various diseases, including several types of cancers, AIDS, and neurodegeneration, but little is known about its association with glucose metabolism and related diseases." (PMID 36358477, 2022).
COVID-19 (1 paper, 2023). A disease caused by infection with severe acute respiratory syndrome coronavirus 2. "The potential significance of the knockdown of ER-resident selenoproteins like SelenoF in COVID-19 pathogenesis has been discussed previously." (PMID 36978807, 2023).
Glucose intolerance (1 paper, 2023). Glucose intolerance (GI) can be defined as dysglycemia that comprises both prediabetes and diabetes. "In a more recent study, it was shown that such selenoprotein-F knockout mice developed glucose intolerance and insulin reduction and that the deleterious effects induced by a high-fat diet (obesity, hyperglycemia, glucose intolerance, and hepatic steatosis) were markedly increased." (PMID 37373256, 2023).
glucose metabolism disorder (1 paper, 2022). "Contrary to this, we found that SELENOF KO caused obvious glucose metabolism disorder at an earlier age and gradually recovered, even showing mild improvement with age in our study." (PMID 36358477, 2022). "Therefore, our results suggested that SELENOS expression might be specifically affected by SELENOF KO and the glucose metabolism disorder observed in young SELENOF KO mice might be partly due to the abnormal elevation of SELENOS expression." (PMID 36358477, 2022).
Hyperglycemia (1 paper, 2022). An increased concentration of glucose in the blood. "Collectively, these results suggest that SELENOF KO caused the decreased glucose catabolism and the increased gluconeogenesis in mice younger than 16 weeks of age, which might have partially contributed to hyperglycemia." (PMID 36358477, 2022).
steatosis (1 paper, 2021). Increased lipid within the cytoplasm of cells. "Amongst the 13 genes, eight (DIO1, GPX2, SEPHS2, SELENOK, SELENOS, SELENOT, SELENOF, and SELENOW) had higher, and five (DIO3, GPX1, SELENON, SELENOO, and TXNRD3) had lower expression in steatosis." (PMID 34869521, 2021).
cancer (26 papers, 2011 to 2025). A tumor composed of atypical neoplastic, often pleomorphic cells that invade other tissues. "Particularly, the interaction between genetic factors and the dietary selenium intake seems to be effective in determining cancer risk and outcome via the metabolism of pivotal selenoproteins such as SelP, SelF (Selenoprotein F), GPx4, and GPx1." (PMID 35204134, 2022). "The gene of SELENOF is located on chromosome 1p31, a locus where deletions or mutations are frequently discovered in cancer cases." (PMID 31109102, 2019). "SELENOF can be regulated by both Se status (as indicated also in our study) and endoplasmic reticulum (ER) stress, and several SELENOF genetic variants have been associated with an altered risk at the different cancer sites, including CRC." (PMID 30469315, 2018). "Research has demonstrated that selenoproteins, such as selenoprotein P (SelP), glutathione peroxidase (GPx), thioredoxin reductase (TXNRD), and selenoprotein F (SEP15, SelF), exert regulatory effects on tumorigenesis and tumor progression through modulation of cancer-associated signaling pathways." (PMID 39839762, 2024). "Current studies have revealed the connections between SELENOF polymorphisms and various risks of cancers, including colorectal cancer, lung cancer, breast cancer, and prostate cancer, yet the results from different populations can be conflicting and inconclusive." (PMID 31109102, 2019). "Like other selenoproteins, the role for SELENOF in carcinogenesis has been investigated due to its altered expression compared to the corresponding normal tissue, its molecular function, and the association of genetic variations in the SELENOF gene to cancer risk or outcome." (PMID 36979420, 2023). "Selenoprotein F (SELENOF) might play an important role in maintaining human health since an increasing number of studies have linked SELENOF deficiency to various pathologies such as cancer and neurodegeneration." (PMID 36358477, 2022). "Additional research will be crucial in elucidating the comprehensive role of Selenoprotein F across various cancer types, aiming to reconcile the seemingly contradictory data and to establish a more definitive understanding of its impact on oncogenesis." (PMID 39839762, 2024). "The impact of Selenoprotein F expression on tumorigenesis has been a subject of investigation across various cancer types." (PMID 39839762, 2024). "Although little is known about the specific roles of selenoprotein M, its functional homolog selenoprotein F (SELENOF) has been shown to be involved in cancer progression." (PMID 37741974, 2023). "For some proteins, e.g., SELENOF and GPX4, the encoded polymorphisms that are associated with cancer risk results in variations within the 3-UTR of the mRNA that controls UGA recoding and readthrough." (PMID 32806741, 2020). "Besides redox control, biosynthesis and quality control of secretory and membrane-associated proteins depend on the function of a set of at least seven cancer-relevant ER-resident selenoproteins, namely SELENOF, I, K, M, N, S, and T." (PMID 40435558, 2025). "However, SEPs such as selenoprotein P (SELP), glutathione peroxidases, thioredoxin reductases (TXNRD) and selenoprotein F (SEP15) have been shown to be able to regulate tumorigenesis through impacting cancer-related signaling proteins." (PMID 35721477, 2022). "However, several studies also indicated that some selenoproteins, namely important cellular redox regulators TXNRD1, SELENOF, and GPx2, may both prevent and promote cancer." (PMID 34829750, 2021). "One such protein, selenoprotein F (SELENOF), for which there is considerable evidence in cancer outcomes, is the focus of this review." (PMID 36979420, 2023). "Selenoproteins that are directly or indirectly linked to redox homeostasis maintenance, such as GPXs, TXNRD1, SELENOF, and SELENOP appear to affect multiple signalling pathways involved in cancer initiation and progression." (PMID 35204134, 2022).
cancer (continued). "Overall, it is demonstrated that two selenoproteins, SELENOF (SelF) and SELENOP (SelP), are only positively correlated with ZIP8 across multiple cancer types (23/40 and 19/40, respectively)." (PMID 34768831, 2021). "Through our analysis, we confirmed higher levels of GPX2 and TXNRD1, and lower levels of GPX1, SELENOF, and SELENOP in the cancer cell lines compared to normal epithelial cells, which has already been observed and reported in the literature." (PMID 32933107, 2020). "Notably several of these genes are ER-resident selenoproteins (SELENOF, SELENOM, SELENON, SELENOT), thought to be involved in ER-stress response and calcium flux, comprising a potentially important mechanism of selenoprotein-related cancer prevention or promotion." (PMID 31027226, 2019).
tumor (12 papers, 2010 to 2025). "Lastly, five genes including GSKIP, SELENOF, RAP1B, UBE2D3, and GTF2B, were found to be co-expressed in both adjacent healthy tissue and tumor tissue." (PMID 37365287, 2023). "Only positive correlations of gene expression with the Se level were observed for the SELENOF, SELENOK, and TXNRD1 genes, all in the tumor tissue (p = 0.001, 0.004, and 0.04, respectively), except for the normal tissue expression of SELENOK as well (p = 0.03)." (PMID 30469315, 2018).
infection (1 paper, 2022). The state of being infected such as from the introduction of a foreign agent such as serum, vaccine, antigenic substance or organism. "Recently, infection of selenium-deficient Vero E6 cells with SARS-CoV-2 revealed a downregulation of SELENOF, SELENOK, SELENOM, and SELENOS localized in the ER, indicating that infection could adversely affect ER." (PMID 35563199, 2022).
SELENOF also shares sentences with these, for which no sentence is quoted: lung carcinoma (4 papers); breast tumor (3); rectal cancer (3); adenoma (1); cardiovascular disease (1); cataract (1); colorectal (1); HIV-1 infection (1); hypercholesterolaemia (1); intestinal cancer (1); Lewis lung carcinoma (1); nuclear cataract (1); Parkinson’s (1); prostate tumors (1); virus infection (1).